SUMO1P3 (SUMO1 pseudogene 3)
Gene: Transcribed processed pseudogene on chromosome 1 (160,317,403 to 160,317,706, forward strand). Ensembl gene ENSG00000235082.
Diseases named in the same sentence as SUMO1P3 in open-access papers:
SUMO1P3 is named in the same sentence as 20 diseases in open-access papers, as found by Europe PMC text mining. Sharing a sentence is not in itself a finding about the gene and the disease. The quoted sentences say what the papers report.
gastric cancer (13 papers, 2013 to 2026). A primary or metastatic malignant neoplasm involving the stomach. "Recent studies have revealed that an increased expression of small ubiquitin-like modifier 1 pseudogene 3 (SUMO1P3) is associated with a lower survival rate in gastric cancer." (PMID 41362671, 2026). "SUMO1P3, a small ubiquitin‐related LncRNA, is also closely associated with the clinicopathological characteristics of patients with gastric cancer." (PMID 33145980, 2020). "HOTAIR, GCAT1 (gastric cancer-associated transcript 1), H19, and SUMO1P3 (small ubiquitin-like modifier SUMO 1 pseudogene 3) are the main lncRNAS reported as overexpressed in gastric carcinomas." (PMID 26448935, 2015). "This implies that SUMO1P3 has the potential to be a valuable predictive biomarker and a novel therapeutic target for gastric cancer." (PMID 41362671, 2026). "The results show that SUMO1P3 promotes proliferation, invasion, and resistance to cisplatin and 5-fluorouracil in gastric cancer cells through its interaction with CNBP." (PMID 41362671, 2026). "The lncRNA SUMO1P3 enhances proliferation, invasiveness, and drug resistance in gastric cancer cell lines by directly binding to CNBP, resulting in high levels of c-myc and cyclinD1 (CCND1)." (PMID 35991559, 2022). "The expression of SUMO1P3 is significantly higher in gastric cancer than that of paracarcinoma tissue; additionally, SUMO1P3 can also be used as a marker to distinguish benign gastric ulcer, gastric polyp and gastric cancer." (PMID 33145980, 2020). "Small ubiquitin-like modifier (SUMO) 1 pseudogene 3, (SUMO1P3) is a novel indentified lncRNA that was previously reported to be up-regulated in gastric cancer." (PMID 26799188, 2016). "Small ubiquitin-like modifier 1 pseudogene 3 (SUMO1P3) is a novel indentified long non-coding RNA that was originally identified as a potential prognostic and therapeutic target for gastric cancer." (PMID 26799188, 2016). "LncRNA SUMO1P3 was previously reported to be up-regulated in gastric cancer." (PMID 26799188, 2016). "Besides, SUMO1 pseudogene 3 (SUMO1P3), a member of the SUMO pseudogene family that expresses lncRNA, is up-regulated in gastric cancer, which correlated with tumor size, differentiation, metastasis and invasion." (PMID 37777749, 2023). "It was found to be upregulated in human gastric cancer tissues compared with paired-adjacent non-tumorous tissues thus, SUMO1P3 could be useful as a biomarker and a therapeutic target for GC." (PMID 30018188, 2018).
bladder cancer (7 papers, 2016 to 2024). "The molecular mechanism underlying SUMO1P3 upregulation in bladder cancer is still to be studied in future works." (PMID 26799188, 2016). "SUMO1P3 is a pseudogene that was found to be upregulated in bladder cancer, and its expression was positively correlated with greater histological grade as well as in other tumor tissues, such as gastric, colon, breast, and liver cancers." (PMID 38846969, 2024). "We proved for the first time that SUMO1P3 can be detected in urine and that its presence is correlated with bladder cancer grade and stage, resulting in a promising, non-invasive biomarker for tumor progression." (PMID 38846969, 2024). "Previous literatures reported that SUMO1P3 is a potential biomarker in the diagnosis of gastric and bladder cancers and that SUMO1P3 promotes bladder cancer growth and metastasis." (PMID 33902004, 2021). "Reportedly, SUMO1P3 promotes the proliferation, migration, invasion, and apoptosis resistance of bladder cancer cells." (PMID 33902004, 2021). "SUMO1P3 was increased in bladder cancer and its high expression predicted poor prognosis of patients with bladder cancer." (PMID 32185172, 2020). "In order to understand the biological functions of lncRNA SUMO1P3, we detected the cell proliferation, apoptosis and migration by silencing SUMO1P3 in the related bladder cancer cell lines." (PMID 26799188, 2016). "Up-regulated SUMO1P3 expression has been associated with poor prognosis, likely due to the ability of SUMO1P3 to induce cell growth and metastasis in bladder cancer cells." (PMID 26799188, 2016). "Our data suggest that SUMO1P3 plays oncogenic roles in bladder cancer and can be used as a potential prognostic and therapeutic target." (PMID 26799188, 2016). "SUMO1P3 was up-regulated in bladder cancer tissues compared to pair-matched adjacent normal tissues." (PMID 26799188, 2016). "Since SUMO1P3 has been demonstrated to bind to miR-320a in breast cancer and hepatocellular carcinoma facilitating tumor progression, we investigated the presence of miR-320a in the urine of bladder cancer patients and controls." (PMID 38846969, 2024). "Furthermore, after knockdown of SUMO1P3, bladder cancer exhibited cell proliferation and migration inhibition and apoptosis induction." (PMID 32185172, 2020). "Cumulatively, these findings indicate that SUMO1P3 play an oncogenic role in bladder cancer and SUMO1P3 may be used as a potential prognostic and therapeutic target of bladder cancer." (PMID 26799188, 2016). "Furthermore, SUMO1P3 was up-regulated in bladder cancer cell lines compared to normal urothelial cell line." (PMID 26799188, 2016). "Further experiments indicated that silencing lncRNA SUMO1P3 could inhibit proliferation, induce apoptosis and suppress migration of the bladder cancer cell lines." (PMID 26799188, 2016). "Furthermore, we found cell proliferation / migration inhibition and apoptosis induction were also observed in SUMO1P3 siRNA-transfected bladder cancer cells." (PMID 26799188, 2016). "We further determined whether SUMO1P3 promotes cell proliferation in bladder cancer." (PMID 26799188, 2016). "We determined whether SUMO1P3 can inhibit cell apoptosis in bladder cancer." (PMID 26799188, 2016). "We hypothesized that SUMO1P3 also have roles in bladder cancer." (PMID 26799188, 2016). "In conclusion, we have shown that SUMO1P3 is increased in the urine of patients with high-grade NMIBC and MIBC and that it is a good candidate for monitoring bladder cancer progression." (PMID 38846969, 2024). "We have shown that the lncRNA SUMO1P3 is increased in urine from patients with high grade NMIBC and MIBC and that it is likely to be good candidate to predict bladder cancer progression if used alone or in combination with UCA1 or with miRNA320a." (PMID 38846969, 2024). "We found reduced miR-320a in the urine of bladder cancer patients with high-grade NMIBC and MIBC, correlating with a greater amount of SUMO1P3." (PMID 38846969, 2024).
bladder cancer (continued). "For example, it is reported that lncRNA PVT1, SUMO1P3 and CCAT2 can facilitate cell proliferation as well as repress cell apoptosis in bladder cancer." (PMID 33855047, 2021). "For example, lncRNAs MALAT1, SUMO1P3, and CCAT2 have been reported to promote cell proliferation and suppress cell apoptosis in bladder cancer." (PMID 33537343, 2020). "Finally, we determined whether SUMO1P3 promotes cell migration in bladder cancer." (PMID 26799188, 2016). "However, the relationship between lncRNA SUMO1P3 and bladder cancer is completely unknown." (PMID 26799188, 2016). "Furthermore, the relationship between SUMO1P3 and bladder cancer is completely unknown." (PMID 26799188, 2016). "Bladder cancer 5637, T24 and UM-UC-3 cells were transfected with SUMO1P3 siRNA or negative control siRNA and the cell migration changes of bladder cells were determined by both wound healing assay and transwell assay." (PMID 26799188, 2016). "Bladder cancer 5637, T24 and UM-UC-3 cells were cultured and transfected with SUMO1P3 siRNA or negative control siRNA." (PMID 26799188, 2016). "Bladder cancer 5637, T24 and UM-UC-3 cells were transfected with SUMO1P3 siRNA or negative control siRNA and the cell proliferation changes of bladder cells were determined using both CCK-8 assay and Edu assay." (PMID 26799188, 2016). "In this study, we found that lncRNA SUMO1P3 was up-regulated in bladder cancer compared with paired-adjacent nontumorous tissue and up-regulated SUMO1P3 expression was positively correlated with greater histological grade and advanced TNM stage." (PMID 26799188, 2016). "In this study, we found that SUMO1P3 was significantly up-regulated in bladder cancer tissues compared with paired-adjacent nontumorous tissues in a cohort of 55 bladder cancer patients." (PMID 26799188, 2016). "In conclusion, the expression level of the lncRNA SUMO1P3 is increased in bladder cancer tissues compared with paired-adjacent nontumorous tissues." (PMID 26799188, 2016). "Bladder cancer 5637, T24 and UM-UC-3 cells were transfected with SUMO1P3 siRNA or negative control siRNA." (PMID 26799188, 2016). "In the present study, we found that lncRNA SUMO1P3 was significantly up-regulated in bladder cancer tissues compared with paired-adjacent nontumorous tissues in a cohort of 55 bladder cancer patients." (PMID 26799188, 2016). "In addition, we demonstrated that SUMO1P3 could discriminate unrelated diseases, such as BPH, from aggressive bladder cancer." (PMID 38846969, 2024). "The overall results demonstrated that SUMO1P3 is a highly specific biomarker for bladder cancer in non-invasive liquid biopsy analysis and can discriminate low-grade from high-grade NMIBC and MIBC, which represent aggressive and invasive phenotypes of the tumor." (PMID 38846969, 2024).
breast cancer (4 papers, 2020 to 2025). A primary or metastatic malignant neoplasm involving the breast. "SUMO1P3 is highly expressed in breast cancer tissues and linked to tumor progression and poor survival." (PMID 40556338, 2025). "Recently, SUMO1P3 has been associated with miR-320a in the development of breast cancer and hepatocellular carcinoma." (PMID 38846969, 2024). "The tumor-promoting effects of SUMO1P3 in breast cancer are at least partly mediated by negative regulation of miR-320a." (PMID 38846969, 2024).
colon cancer (3 papers, 2020 to 2025). "SUMO1P3 promotes colon cancer by enhancing proliferation, modulating the cell cycle, activating oncogenic pathways, and driving angiogenesis, while its reduction suppresses tumor growth and metastasis." (PMID 40556338, 2025). "The mechanism of SUMO1P3 in colon cancer involves regulating cell proliferation, modulating cell cycle progression, influencing key oncogenic pathways, and promoting angiogenesis." (PMID 40556338, 2025). "For example, the lncRNA small ubiquitin-like modifier 1 pseudogene 3 (SUMO1P3) is overexpressed in colon cancer, and is positively related to angiogenesis, metastases, advanced histological stages, and unfavorable outcome of colon cancer patients." (PMID 32117736, 2020). "Inhibition of SUMO1P3 repressed proliferation, migration, invasion and pro-angiogenesis of colon cancer cells in vitro, and reduced growth, liver metastasis and vascularization of colon cancer in vivo by decreasing cyclin D1, vimentin and VEGFA but increasing E-cadherin expression." (PMID 32185172, 2020).
hepatocellular carcinoma (3 papers, 2020 to 2024). A malignant tumor that arises from hepatocytes. "In this study, we aimed to investigate expression profile of long non‐coding RNA (lncRNA) SUMO1P3, and its role and molecular mechanisms in the progression of hepatocellular carcinoma (HCC)." (PMID 31970876, 2020).
pancreatic cancer (3 papers, 2020 to 2021). "Additionally, the data indicated that the elevated expression of SUMO1P3 is significantly associated with tumor progression and the poor survival of individuals with pancreatic cancer." (PMID 34947885, 2021). "Functional experiments revealed the enhanced effect of SUMO1P3 on proliferation, migration and invasion of pancreatic cancer." (PMID 32185172, 2020). "They found that SUMO1P3 expression was markedly elevated in pancreatic cancer tissues when compared with normal controls." (PMID 32185172, 2020). "In addition, lncRNA SUMO1P3 promotes cell proliferation, migration, and invasion of pancreatic cancer." (PMID 33865422, 2021). "SUMO1P3 knockdown may suppress the proliferation, migration, and invasion of pancreatic cancer cells." (PMID 34947885, 2021).
liver cancer (2 papers, 2021 to 2022). An epithelial or non-epithelial malignant neoplasm that arises from the liver. "The lncRNA SUMO1P3 serves as an advantageous predictor of liver cancer prognosis and a potent therapeutic target." (PMID 35874626, 2022). "The Wnt/β-catenin signaling pathway promotes the progression of liver cancer through the activation of SUMO1P3 lncRNA by targeting miR-320a." (PMID 33869042, 2021).
lymph node metastasis (2 papers, 2020 to 2021). "We found that the levels of SUMO1P3 mRNA were positively correlated with lymph node metastasis (P = .027) and TNM stage (P = .019)." (PMID 31970876, 2020).
non-small cell lung carcinoma (2 papers, 2020 to 2023). A group of at least three distinct histological types of lung cancer, including non-small cell squamous cell carcinoma, adenocarcinoma, and large cell carcinoma. "In non-small cell lung cancer (NSCLC), SUMO1P3 is associated with clinical progression, and it promotes cell migration and invasion by binding and suppressing miR-136, an anti-oncogenic miRNA in human cancers." (PMID 36835116, 2023). "Recent research found that the expression level of SUMO1P3 was significantly upregulated in non-small cell lung cancer cell lines and cancer tissues." (PMID 32185172, 2020). "Moreover, SUMO1P3 enhanced cell migration and invasion of non-small cell lung cancer." (PMID 32185172, 2020).
benign prostate hyperplasia (1 paper, 2024). "SUMO1P3 and UCA1 expression in urine was able to significantly discriminate low grade NMIBC, healthy control and benign prostatic hyperplasia subjects versus high grade NMIBC and MIBC patients." (PMID 38846969, 2024).
bladder tumors (1 paper, 2024). "The overall data obtained from this first patient cohort demonstrated that SUMO1P3 is a good biomarker for discriminating bladder tumors with aggressive phenotypes from healthy low-grade NMIBC." (PMID 38846969, 2024).
glioma (1 paper, 2022). A benign or malignant brain and spinal cord tumor that arises from glial cells (astrocytes, oligodendrocytes, ependymal cells). "SUMO1P3 is also elevated in gliomas and associates with poor survival of glioma patients." (PMID 35402278, 2022).
urothelial bladder cancer (1 paper, 2016). "The relative expression level of SUMO1P3 was determined by using Real-Time qPCR in a total of 55 patients with urothelial bladder cancer and different cell lines." (PMID 26799188, 2016).
tumor (10 papers, 2016 to 2025). "High SUMO1P3 expression was positively associated with tumor growth and metastasis and predicted poor outcomes in HCC patients." (PMID 33902004, 2021). "However, we know nothing about the biological function and underlying mechanism of SUMO1P3 in tumor." (PMID 26799188, 2016). "Reducing SUMO1P3 levels in animal models leads to decreased tumor growth, metastasis, and changes in key protein expression patterns." (PMID 40556338, 2025). "It promotes tumor growth, metastasis, and angiogenesis, and SUMO1P3-knockdown inhibits cell proliferation and migration while inducing apoptosis." (PMID 38846969, 2024). "Since miR-320a levels were supposed to be lower in tumor samples than in healthy controls and inversely correlated with SUMO1P3 levels, we determined the capacity of the SUMO1P3/miR-320a ratio in discriminating cases from controls." (PMID 38846969, 2024). "ROC curve analysis showed that SUMO1P3 is a promising biomarker for predicting aggressive tumor phenotypes, with an area under the curve (AUC) of 0.848 (low- vs high-grade NMIBC) and 0.878 (low-grade NMIBC vs MIBC)." (PMID 38846969, 2024). "Five oncogenic (LUCAT1, MIR31HG, UCA1, HIF1A-AS2, and SUMO1P3) and tumor-suppressive (LINC00312) lncRNAs were independently validated, and three key molecules were further examined." (PMID 36980216, 2023). "Compared with control or shNC group, SUMO1P3-depleted group exhibited significant reduction in tumor volume." (PMID 33902004, 2021). "SUMO1P3 enhancement was positively related to tumor size and number, poor differentiation, lymphatic and distant metastasis, TNM stage, and poor outcome of HCC patients." (PMID 33902004, 2021). "High expressions of SUMO1P3 were positively correlated with some clinicopathological parameters, including tumor size and number, poor differentiation, lymphatic and distant metastases, and TNM stage." (PMID 33902004, 2021). "Second, SUMO1P3 upregulation was closely correlated with tumor size and number, poor differentiation, lymphatic and distant metastasis, TNM stage, and poor outcomes of HCC patients." (PMID 33902004, 2021). "In this study, we revealed that SUMO1P3 expression was enhanced in HCC tissues and cell lines, positively associating with tumor size and number, poor differentiation, lymphatic and distant metastasis, TNM stage, and poor prognosis in HCC patients." (PMID 33902004, 2021). "SUMO1P3 acts by binding and suppressing the tumor suppressor miR‐320a, promoting tumor growth." (PMID 40556338, 2025). "Interestingly, SUMO1P3 negatively regulates miR-320a which has tumour suppressive qualities and is found in the EVs of patients with smaller, early-stage BC tumours." (PMID 37670020, 2023). "SUMO1P3-silenced mice showed slow tumor growth compared to the control or shNC-treated animals." (PMID 33902004, 2021). "Consistently, SUMO1P3 depletion in HCC cells retarded tumor growth and lung metastasis in vivo." (PMID 33902004, 2021). "Therefore, a higher level of SUMO1P3 combined with a lower level of miR-320a could be used in combination as a prognostic marker for more aggressive BC tumours." (PMID 37670020, 2023). "In conclusion, lncRNA SUMO1P3 is up‐regulated in HCC specimens and positively correlated with metastasis and tumour stage." (PMID 31970876, 2020). "However, the expression of SUMO1P3 was not influenced by HCC patients' age, gender, smoking, drinking habits or tumour size (P > .05 for all)." (PMID 31970876, 2020).
cancer (9 papers, 2016 to 2026). A tumor composed of atypical neoplastic, often pleomorphic cells that invade other tissues. "Furthermore, we know nothing about the biological function and underlying mechanism of lncRNA SUMO1P3 in cancers." (PMID 26799188, 2016). "Researchers have confirmed that the lncRNA SUMO1P3 is substantially up-regulated in multiple cancer types, including colon, bladder, breast, and liver cancer." (PMID 41362671, 2026). "An analysis of the Cancer Genome Atlas (TCGA) dataset revealed that the lncRNA small ubiquitin-like modifier 1 pseudogene 3 (SUMO1P3) is upregulated in breast cancer tissues." (PMID 36835116, 2023). "The oncogenic roles of SUMO1P3 indicate that it may be a valuable prognostic biomarker and a potential therapeutic target for cancer patients." (PMID 41362671, 2026). "SUMO1P3 is a novel identified lncRNA that was up-regulated in several types of cancer, including gastric cancer, bladder cancer, and non-small cell lung cancer, and is a prognostic and therapeutic target these cancers 97-99." (PMID 33390845, 2021).
SUMO1P3 also shares sentences with these, for which no sentence is quoted: colorectal cancer (1 paper); gastric polyp (1); lung carcinoma (1); pancreatic (1); prostate carcinoma (1).